Y_RNA (Y RNA )
Gene: Miscellaneous RNA gene on chromosome 5 (154,705,626 to 154,705,727, forward strand). Ensembl gene ENSG00000274472.
Homologues: Orthologues: chimpanzee Y_RNA (97% identical), zebrafish Y_RNA (63% identical). Paralogues in human: Y_RNA (64% identical), Y_RNA (60% identical), Y_RNA (58% identical), RNY1P5 (57% identical), Y_RNA (57% identical), Y_RNA (56% identical), Y_RNA (55% identical), Y_RNA (54% identical), RNY1P14 (53% identical), RNY1P6 (53% identical), Y_RNA (53% identical), Y_RNA (52% identical), and 82 more.